ESR1 (estrogen receptor 1)
Diseases named in the same sentence as ESR1 in open-access papers (continued):
Sharing a sentence is not in itself a finding about the gene and the disease.
breast cancer (continued). "Single nucleotide polymorphisms (SNPs) in the estrogen receptor gene (ESR1) play critical roles in breast cancer (BC) susceptibility." (PMID 27070141, 2016). "Advanced breast cancer patients with baseline ESR1 mutations treated with fulvestrant have been shown to have improved outcomes compared with exemestane." (PMID 27903276, 2016). "ESR1 is an important mediator of endocrine pathways involved in breast cancer risk and outcomes, including endocrine treatment response and side effects." (PMID 27825388, 2016). "A recent meta-analysis found that menopausal status modifies breast cancer risk associated with ESR1 PvuII (C > T), with premenopausal variant carriers being at higher risk, possibly related to differences in circulating estrogen levels." (PMID 27825388, 2016). "We formally modeled this relationship and determined that, for every 1% decrease in ESR1 expression, 15 more mutations are expressed in breast cancer." (PMID 27498871, 2016). "BAHD1-mediated regulation of ESR1 is also enticing as ESR1 is a key regulator in a variety of biological processes and ESR1 deregulation has been implicated in several diseases, including breast cancer." (PMID 26938916, 2016). "Recently, somatic mutations in the ERα gene (ESR1) were linked to acquired resistance to endocrine therapies of breast cancer." (PMID 26836308, 2016). "We aimed to investigate the clinical significance of sequential measurements of ESR1 mutations in primary breast cancer (PBC) and metastatic breast cancer (MBC) patients." (PMID 27102299, 2016). "The association between variant allele T of ESR1 PvuII (C > T) and breast cancer appears to be linked to a higher transcriptional activity of the variant gene and correlated with circulating estrogen levels." (PMID 27825388, 2016). "We applied the MINDy (Modulator Inference by Network Dynamics) algorithm to four TFs (ESR1, FOXA1, GATA3 and SPDEF) that are key drivers of estrogen receptor-positive (ER+) breast cancer risk, as well as cancer progression." (PMID 27997592, 2016). "In fact, several studies suggest that the effect of the ESR1 polymorphisms on breast cancer risk is hormone-related and dependent on the woman’s hormonal context, showing statistically significant associations mainly in premenopausal women." (PMID 27825388, 2016). "In conclusion, our study demonstrates that ddPCR monitoring of recurrent ESR1 mutations in cfDNA of breast cancer patients is feasible and is a useful method of providing relevant predictive information." (PMID 27102299, 2016). "Of these variants, a recent report found novel associations between breast cancer SNPs in 6q25 including rs9383938 in the ESR1 region with a volumetric measure of mammographic density in 5000 Swedish women." (PMID 27717337, 2016). "Single nucleotide polymorphisms (SNPs) involved in the estrogen pathway and SNPs in the estrogen receptor alpha gene (ESR1 6q25) have been linked to breast cancer development, and mammographic density is an established breast cancer risk factor." (PMID 27717337, 2016). "Second, the metastatic pattern/ and behavior of ESR1 positive lung cancer is similar to breast cancer, where bone metastases are associated with estrogen receptor positivity." (PMID 25928859, 2015). "Recently, a genomic analysis of the PD-L1 gene in breast cancer showed that the PD-L1 gene was inversely associated with the ESR1 gene in 5,454 breast cancers profiled using DNA microarrays." (PMID 26378017, 2015). "All these results suggest that ESR1 mutations are rare in newly diagnosed, untreated breast cancers but appear to be frequently acquired during progression to hormone resistance, especially in the context of estrogen deprivation therapy." (PMID 26059247, 2015). "One such gene, oestrogen receptor alpha (ESR1), is of crucial importance in terms of both diagnostic and prognostic implications in breast cancer." (PMID 25927974, 2015).
breast cancer (continued). "Genetic alterations in estrogen receptor alpha gene (ESR1) such as C325G single nucleotide polymorphism (SNP) are thought to play a role in predisposition to breast cancer." (PMID 25641872, 2015). "Several reports have recently described the appearance of somatic ESR1 mutations as a potential mechanism of secondary endocrine resistance in HR+ breast cancer." (PMID 26059247, 2015). "Early detection of the ESR1 mutation with ddPCR in breast cancer biopsies allowed for the cessation of ineffective endocrine therapies and the initiation of other treatments without the need for tissue biopsy." (PMID 26485760, 2015). "Meanwhile, the ESR1, estrogen receptor encoding gene, has been proved to be involved in pathological processes including breast cancer and endometrial cancer." (PMID 26425543, 2015). "A relevant example is high ESR1 expression, which is associated with good prognosis in breast cancer (and marks the Luminal A subclass), but is required for growth and is an excellent therapeutic target." (PMID 26183823, 2015). "Taken together, our data confirm that, as for breast cancer, ESR1 expression in lung cancer is associated with the lower levels of EMT Markers." (PMID 25928859, 2015). "Previous GWAS and candidate approaches have identified multiple genetic variants at CCDC170/ESR1 to be associated with breast cancer as well as mammographic density." (PMID 26036842, 2015). "Resistance to aromatase inhibitors develops in almost half of estrogen receptor (ER) positive breast cancer patients who acquire ESR1 mutations." (PMID 26474073, 2015). "It is gratifying that multiple laboratories studying diverse patient populations with advanced, treatment-resistant breast cancer have verified ESR1 mutations, thus validating those who suggested their existence nearly 30 years ago." (PMID 25928204, 2014). "Researchers in numerous studies have evaluated the associations between variants in ESR1 and breast cancer risk." (PMID 25116933, 2014). "A genomic study reported that a gene signature developed fromPIK3CA mutant human breast cancers was associated with low mTORC1 outputand high ESR1 signaling." (PMID 25192370, 2014). "We performed a GWAS for breast cancer in Latinas and identified an association between two linked variants within the 6q25 region, 5′ of the ESR1 gene and breast cancer risk." (PMID 25327703, 2014). "ESR1 is a strong candidate susceptibility gene related to breast cancer in the 6q25.1 region (encoding estrogen receptor α), and studies have shown its implication in breast carcinogenesis." (PMID 25116933, 2014). "From the inhibition of ESR1, the hormone would be regulated then decreased the risk for hormone breast cancer." (PMID 25054138, 2014). "Apart from two tag SNPs for ESR1, another six SNPs (rs11552449, rs13387042, rs10759243, rs3903072, rs12422552, rs2236007) were also significantly associated with breast cancer in our study." (PMID 24941967, 2014). "Subsequently, one intronic variant, rs3757318 in CCDC170, and another intronic rs9383951 in ESR1, were also found to be associated with breast cancer risk." (PMID 25116933, 2014). "Here we carry out a genome-wide association study of breast cancer in Latinas and identify a genome-wide significant risk variant, located 5′ of the Estrogen Receptor 1 gene (ESR1; 6q25 region)." (PMID 25327703, 2014). "Here we review recent advances in detection and characterization of ESR1 mutations in advanced, endocrine therapy-resistant breast cancers." (PMID 25928204, 2014). "We report the discovery of a genome-wide significant breast cancer-protective variant of Indigenous American origin (rs140068132), located 5′ of the Estrogen Receptor 1 gene (ESR1; 6q25 region)." (PMID 25327703, 2014). "Specifically, the CCDC170 rs9383935 showed the most prominent effect of any other variants of ESR1 or rs2046210, which provides new evidence for the role of the 6q25.1 region in breast cancer susceptibility." (PMID 25116933, 2014).
breast cancer (continued). "Polymorphism in the intron 1 of the ESR1 gene (rs2234693), also called ESR1 PvuII, was associated with increased risk of breast cancer and decreased ER expression." (PMID 23951298, 2013). "Among the breast cancer-associated SNPs found in the current study, rs2046210 and rs3757318 are located near ESR1 and are related to breast cancer risk in Asians." (PMID 24289300, 2013). "In this case, the lack of ESR1 methylated samples makes it impossible to prove the association between ESR1’s methylation and expression in breast cancer." (PMID 23742247, 2013). "The identified association of ESR1 to CMT in the present survey supports the power of the canine model for human breast cancer and the fact that combined studies within and between breeds can add power to the detection of risk alleles also for complex traits." (PMID 23574728, 2013). "Single nucleotide polymorphisms (SNPs) in the ESR1 gene have been associated with increased susceptibility to breast cancer, however they are fairly rare." (PMID 23894323, 2013). "In Japanese women, rs2046210 and 3757318 located near the ESR1 gene are associated with a risk of breast cancer, as in other Asian women." (PMID 24289300, 2013). "Previous studies on human breast cancer have suggested that ESR1 polymorphisms are associated with the development of these tumours." (PMID 23574728, 2013). "Proteasome activity is increased in cancer and we previously showed that proteasome inhibition leads to loss of ESR1 gene expression in breast cancer cells." (PMID 24339902, 2013). "Continuous variable analysis of ESR1_TA, ESR2_CA, and AR_CAG alleles and breast cancer risk in African American and Nigerian women." (PMID 22792352, 2012). "Our laboratory observed Blimp1 expression in breast cancer cells, and showed it repressed transcription of the ESR1 gene encoding estrogen receptor alpha (ERα), thereby promoting a more migratory phenotype." (PMID 22438909, 2012). "Of particular interest in breast cancer is the ESR1 gene, which encodes the oestrogen receptor alpha protein, which we have used to illustrate intragenic DNA methylation from whole-genome bisulphite sequencing data." (PMID 22166804, 2012). "Summary of the literature about ESR1_TA, ESR2_CA, and AR_CAG microsatellites and breast cancer risk." (PMID 22792352, 2012). "SNPs rs9383951, located in intron 5 of the estrogen receptor 1 (ESR1) gene, and rs7107217, located at 11q24.3, were also consistently associated with breast cancer risk in all four stages with a combined P of 1.9×10−6 and 4.6×10−7, respectively." (PMID 22383897, 2012). "Genome-wide association studies have reported that a polymorphism near the estrogen receptor gene (ESR1) (rs2046210) is associated with a risk of breast cancer, with the A allele conferring an increased risk." (PMID 23272245, 2012). "A network of genes that co-express with ESR1, the estrogen receptor gene, has also been linked to decreased breast cancer recurrence risk in several published studies and also emerges in our RNA-Seq results." (PMID 22808097, 2012). "Previous candidate gene studies have extensively evaluated two SNPs, rs2234693 (Pvull) and rs9340799 (XbaI), in the ESR1 gene in relation to breast cancer risk; the results, however, have been inconsistent." (PMID 22383897, 2012). "It is conceivable that the common sequence variations in the ESR1 gene affect the risk of different disease phenotype, such as breast cancer, osteoarthritis, cardiovascular disease, and migraine." (PMID 22727021, 2012). "A large case-control study of ESR1 haplotype and postmenopausal breast cancer risk in Sweden has been carried out, but the ESR1_TA genotypes distribution deviated from HWE." (PMID 22792352, 2012). "ER, encoded by ESR1, is an important factor in breast cancer, because studies in females have shown that patients with hormone-negative tumors do not benefit from endocrine therapy." (PMID 22765268, 2012).
breast cancer (continued). "Categorical variable analysis of ESR1_TA, ESR2_CA, and AR_CAG alleles and breast cancer risk in African American and Nigerian women." (PMID 22792352, 2012). "We have identified a previously unreported transcriptional activity hub spanning ESR1, the gene encoding the important breast cancer biomarker oestrogen receptor." (PMID 21552322, 2011). "Our previous study suggested an association between ESR1 polymorphisms and breast cancer risk in the same Swedish sample." (PMID 21269472, 2011). "To confirm this interaction, we used the joint method and calculated the risk of breast cancer associated with both rs12539530 and ESR1 SNPs using a set of dummy variables representing different combinations of genotypes of ESR1 and rs12539530." (PMID 21281495, 2011). "Our findings provide support for a role of ESR1-ERE polymorphism in determining susceptibility of breast cancer development." (PMID 21281495, 2011). "Only recently, through a very large genetic association study, has there been demonstrated a small but significant association of polymorphisms within ESR1 with the risk of breast cancer." (PMID 21269472, 2011). "The objective of the present study was to investigate the association between clinical extension of breast cancer and methylation status of Estrogen Receptor1 (ESR1) and Stratifin (14-3-3-σ) gene promoters in disease-free and metastatic breast cancer patients." (PMID 20487521, 2010). "Included among these are Sirt1, Hey2, Ncoa4, and Foxa1, all of which have been implicated in the progression of luminal breast cancer and ER-α-dependent signaling, as well as ER-α (that is, Esr 1)." (PMID 20565980, 2010). "The estrogen receptor α (ESR1) locus has been a focus of attention because of the roles of estrogen in risk of breast cancer, osteoporosis and other conditions." (PMID 20661439, 2010). "ESR1 is a ligand activated transcription factor, which has been implicated in ovarian and breast cancer." (PMID 19543528, 2009). "Recently, a significant association with familial breast cancer risk has been observed for the C allele of ESR1_rs2747648 in an allele dose-dependent manner." (PMID 20003447, 2009). "Case-control studies of breast cancer risk related to ESR1 rs2234693 and in relation to CYP19A1 rs936306 are conflicting." (PMID 19630952, 2009). "For example, ESR1 rs2234693 has been associated with duration of breast cancer survival, degree of breast cancer differentiation, age at breast cancer diagnosis, and receptor status of breast cancer tumors." (PMID 19630952, 2009). "In that study, ESR1 Ex4-122C>G was shown to be associated with breast cancer and the progression of prostate cancer, which is commensurate with our findings of higher risk for being diagnosed to have advanced disease." (PMID 19654868, 2009). "In our parallel breast cancer study the ESR1-disease risk association was stronger in women with high BMI but this appeared not to be the case in endometrial cancer." (PMID 18990228, 2008). "Most previous publications regarding the ESR1 gene and breast cancer risk have included only a few polymorphisms in the gene." (PMID 18271972, 2008). "One group, who genotyped 17 SNPs in the ESR1 gene, found a decreased risk of breast cancer for carriers of three common haplotypes in the gene and an increased risk for carriers of one common haplotype." (PMID 18271972, 2008). "None of the haplotypes carried SNPs that were located in the region in ESR1 we found to be associated with breast cancer risk." (PMID 18271972, 2008). "Notable but somewhat complex hormonal-driven associations have been reported between other ESR1 gene variants and breast cancer, spontaneous abortion, osteoporosis, age of menarche, genital abnormalities in men and fertility in men and women." (PMID 18636124, 2008).
breast cancer (continued). "A region between TAG26 (rs3003925) and TAG30 (rs2144025) in the ESR1 gene showed a signal for association with breast cancer risk in the multi-locus analysis of five adjacent tagSNPs, but the result did not withstand multiple testing correction." (PMID 18271972, 2008). "One study, however, genotyped 17 common SNPs in the ESR1 gene and found three haplotypes to decrease breast cancer risk and one haplotype that increased the risk." (PMID 18271972, 2008). "We observed two SNPs in the 3' region of ESR1 that are associated with breast cancer risk, namely rs2228480 and rs3798577." (PMID 19094228, 2008). "There was an average 65-fold range in the ESR1 transcript levels across this entire collection of 101 breast cancers, with the ESR1-associated probes showing similar variations." (PMID 17850661, 2007). "The amount of LD between the two ESR1 SNPs was relatively small, with a D' of 0.07 in cases and 0.15 in controls, and none of the four haplotypes was significantly associated with breast cancer." (PMID 16672066, 2006). "A marginally significant decrease in the risk of developing breast cancer was observed among carriers of the ESR1 – 104062T allele compared to carriers of the referent genotype (all participants: OR 0.70, 95% CI 0.45, 1.09)." (PMID 16808847, 2006). "The ESR1 gene encodes ER‐α, which is a key driver in ER(+) breast cancer." (PMID 41510186, 2026). "ERαΔ7 is one of the most frequently observed splice variants of the ESR1 gene in breast cancer but its functions remain largely unknown." (PMID 41703982, 2026). "Activating mutations in the ESR1 gene are a known mechanism of secondary resistance to endocrine therapy in metastatic estrogen receptor-positive (ER+)/human epidermal growth factor receptor 2-negative (HER2−) breast cancers." (PMID 41142848, 2025). "Mutations in the F404 locus of the ESR1 gene have been identified as a specific acquired resistance mechanism conferring resistance to the selective estrogen receptor degrader (SERD) fulvestrant in breast cancer cells." (PMID 39995416, 2025). "Subgroup analysis from the Phase I/II TRINITI-1 trial suggests that the presence of ESR1 mutations is associated with a poorer prognosis in patients with advanced HR+/HER2- breast cancer treated with a combination of exemestane, ribociclib, and everolimus following progression on prior therapies." (PMID 40740245, 2025). "Additionally, according to TCGA data, rs9952980 was found to be significantly associated with reduced SLC14A2 expression in breast cancer patients, likely mediated by its direct impact on ESR1-DNA binding." (PMID 41301792, 2025). "Several of these ESR1 mutation-positive non-breast cancer cases may have a high tumor mutational burden or microsatellite instability, which may explain the presence of ESR1 mutations." (PMID 40282442, 2025). "In addition, we observed that loss of Frmd8 significantly decreased the expression of Esr1 and Pgr in normal cells of mammary tumors and decreased expression of Frmd8 in tumor cells accompanied with low expression of Esr1 and Pgr compared with normal cells." (PMID 40213945, 2025). "Notably, ESR1 gene mutations, which encode ERα, are rare in primary breast cancer but occur in about 20% of patients with metastatic breast cancer (MBC) who have undergone endocrine therapy." (PMID 39757310, 2025). "An ESR1 mutation and PD-L1 and PD-L2 amplification were enriched in R/M breast cancer (all p<0.05)." (PMID 40182039, 2025). "Compared to well-established biomarkers in HR+/HER2− breast cancer, such as ESR1 mutations and PI3K/AKT pathway genes, CEACAM6 may offer complementary predictive value by capturing both chemotherapy sensitivity and immune microenvironment status." (PMID 40936892, 2025).